RNU6-1145P (RNA, U6 small nuclear 1145, pseudogene)
Gene: Small nuclear RNA gene on chromosome 2 (61,605,616 to 61,605,722, forward strand). Ensembl gene ENSG00000206973.
Homologues: Orthologues: chimpanzee U6 (100% identical), macaque U6 (96% identical), guinea pig U6 (93% identical), guinea pig U6 (89% identical), pig U6 (89% identical), guinea pig U6 (86% identical), pig U6 (85% identical). Paralogues in human: RNU6-38P (96% identical), RNU6-1316P (95% identical), RNU6-20P (95% identical), RNU6-393P (95% identical), RNU6-16P (94% identical), RNU6-25P (94% identical), RNU6-29P (94% identical), RNU6-41P (94% identical), RNU6-639P (94% identical), RNU6-1 (93% identical), RNU6-15P (93% identical), RNU6-2 (93% identical), and 1286 more.